SMCHD1 (structural maintenance of chromosomes flexible hinge domain containing 1)
Diseases named in the same sentence as SMCHD1 in open-access papers (continued):
Sharing a sentence is not in itself a finding about the gene and the disease.
cancer (6 papers, 2016 to 2024). A tumor composed of atypical neoplastic, often pleomorphic cells that invade other tissues. "Mutations in Smchd1, which is linked to cancer in mice, hypomethylate the CpG islands of normally inactivated genes, reactivating X.108, 109However, cancer researchers are just beginning to study X‐linked gene epigenetic effects." (PMID 38827026, 2024). "As shown here and previously in vitro and confirmed here in vivo in cancer specimens with a somatic loss of heterozygosity of the 18p locus encompassing SMCHD1, DNAme changes are only triggered by germline SMCHD1 mutations." (PMID 37334829, 2023). "However, as shown in cancer cell lines, somatic SMCHD1 invalidation in human primary fibroblasts does not cause D4Z4 hypomethylation." (PMID 37334829, 2023). "At the same time, pan-cancer analysis also shows that PPM1A, DAPK1, FBP1, PYHIN1, ALPL and SMCHD1 have significant amplification in PCa." (PMID 30867653, 2019).
genetic disease (2 papers, 2023 to 2025). "Our study, along with previous research in animal models, confirms the critical role of SMCHD1 in shaping the mammalian genome and sheds light on the consequences of SMCHD1 mutations in rare genetic diseases." (PMID 37334829, 2023). "Among them, several distinct rare genetic diseases are linked to mutations in SMCHD1 that encodes the structural maintenance of chromosomes flexible hinge domain containing 1 chromatin-associated factor." (PMID 37334829, 2023).
infection (2 papers, 2023 to 2024). The state of being infected such as from the introduction of a foreign agent such as serum, vaccine, antigenic substance or organism. "Depletion of SMCHD1 in HUVEC, a primary endothelial cell line, enhanced the transcription of viral genes and viral genome replication during de novo infection, indicating that SMCHD1 restricts KSHV de novo infection." (PMID 37010434, 2023). "Consistently, the lungs of SMCHD1-deficient mice showed elevated inflammation and more infiltration of immune cells than did those of control mice after MHV68 infection." (PMID 37010434, 2023). "Among these hits, we identified that SMCHD1 was a broad-spectrum restriction factor of AAV infection, depletion of which could enhance AAV transduction of multiple serotypes, and was independent of ssAAV and scAAV genotypes." (PMID 38976714, 2024). "Next, we asked whether SMCHD1 plays a role in KSHV de novo infection." (PMID 37010434, 2023). "Collectively, these data indicated that SMCHD1 restricts KSHV lytic replication and de novo infection." (PMID 37010434, 2023). "KSHV latency could still be established in SMCHD1-depleted HUVEC (data not shown), suggesting that although SMCHD1 suppresses viral replication during de novo infection, the disturbance is insufficient to disrupt KSHV latency establishment." (PMID 37010434, 2023). "We found that the SMCHD1 level was not affected during KSHV de novo infection." (PMID 37010434, 2023).
myopathy (2 papers, 2014 to 2024). A disease of the muscle in which the muscle fibers do not function properly. "Furthermore, a long-read genome sequencing approach may allow for the concurrent detection of pathogenic variants in the gene SMCHD1 that result in the closely related facioscapulohumeral dystrophy type 2 (FSHD2, OMIM 158901) and genotyping at other loci associated with myopathy." (PMID 39669606, 2024).
SMCHD1 also shares sentences with these, for which no sentence is quoted: Anosmia (3 papers); hypogonadotrophic hypogonadism (3); pituitary hormone deficiency (3); Immunodeficiency (2); myotonic dystrophy (2); nasal hypoplasia (2); Septo-optic dysplasia (2); Angelman syndrome (1); Becker muscular dystrophy (1); breast carcinoma (1); cardiomyopathy (1); Chorea (1); coloboma (1); COVID-19 (1); Duchenne muscular dystrophy (1); Dystonia (1); Hearing impairment (1); ICF syndrome (1); infarction (1); Intellectual disability (1); myocardial infarction (1); myoclonic dystonia (1); neuromuscular genetic diseases (1); Spinal Muscular Atrophy (1); viral infection (1); X-linked myotubular myopathy (1).